TNF (tumor necrosis factor)
Diseases named in the same sentence as TNF in open-access papers (continued):
Sharing a sentence is not in itself a finding about the gene and the disease.
breast carcinoma (continued). "For instance, in breast cancer, PTX3 inhibits dihydrotestosterone- and FGF8b-driven cell proliferation, while elevated PTX3 levels, induced by TNF-α stimulation in a bone metastatic breast cancer cell line, promote cell migration, macrophage chemotaxis, and subsequent osteoclast differentiation." (PMID 41479916, 2025). "DIM treatment inhibited TNF‐α/TGF‐β‐regulated EMT in human breast cancer cells without affecting cell viability or proliferation." (PMID 40584407, 2025). "Our results are consistent with this in the context of PD-L1 status and with previously reported correlation of PD-L1 expression in breast cancer with cytotoxic immune response genes and immune-related pathways and features (e.g., IFN-α, IFN-γ, STAT3, and TNFα)." (PMID 39656429, 2025). "Third, cancer cells may also produce factors that affect TNF-α and IFN-γ stability as a mechanism of resistance, such as the metalloproteinase ADAM17, which degrades IFN-γ in MCF-7 and MDA-MB-453 breast cancer cell lines." (PMID 39883638, 2025). "In breast cancer patients, both CRP and TNFα increased with time." (PMID 40014780, 2025). "To ensure the reliability of our data, we used in vitro A549 lung adenocarcinoma and MDA-MB-231 breast cancer triple-negative cell cultures to demonstrate the herb extract’s effects on PI3K and Akt enzymes and clarify how PI3K/Akt/mTOR mediation regulates TNFα, VEGFα, COX-2, MMP-2, and Caspase-3." (PMID 40179064, 2025). "The regulatory mechanisms of CAA in breast cancer are complex, including inflammatory adipokine secretions such as IL-1β, CCL2, TNFα, CCL5, and leptin, as well as IL-6 metabolic reprogramming by altering the metabolism of macronutrients and remodeling of the extracellular matrix." (PMID 39858015, 2025). "Similarly, when co-cultured with breast cancer cells, it was found that CD8+CD69+CD103+TRM exhibited higher levels of IFNG and tumor necrosis factor-alpha (TNF-α) compared to CD8+CD69+CD103−T cells, further mediating a more significant tumor-killing effect." (PMID 38553708, 2024). "Thus, M-DCsTNF combined with an IAP antagonist can be used to treat advanced stage breast cancer and other solid cancers because an IAP antagonist enables TNFα to rapidly induce apoptosis in a broad range of cancers." (PMID 39105847, 2024). "In vitro studies demonstrated that these compounds induce a significant increase of TNF-α, IL-12, IL-6 and IL-1β mRNA expression and downregulate M2-like genes like IL-10, Ym-1, CD206 and Arg-1 in several models of cancer (e.g., breast cancer, colon cancer, MM)." (PMID 38397187, 2024). "The comorbidity-driven inflammation and increasing cytokines, such as TNFα and Groα/CXCL1, might contribute to the early onset of breast cancer in this cohort of AA and LA women." (PMID 38541912, 2024). "Moreover, doxorubicin upregulates CXCL8 and TNF in lung cancer cells and IL12-induced IFNG in xenografted breast cancer." (PMID 39759512, 2024). "ICAM1 expression is exclusive to triple-negative and HER2-positive breast cancer but is induced by proinflammatory cytokines such as TNF–α, IFN–γ, and IL–1β, independent of the tumor hormone receptor status, and is linked to high immune cell infiltration." (PMID 39590296, 2024). "In conclusion, our findings support a cooperativity model in which TGF-β could amplify the TNF-α-mediated MMP-9 production via chromatin remodeling and facilitate breast cancer invasion and metastasis." (PMID 39351229, 2024). "M-DCsTNF plus an IAP antagonist, SM-164, but neither alone, markedly induce MDA-MB-231 breast cancer cell apoptosis, which was blocked by TNF antibody." (PMID 39105847, 2024). "Production of proinflammatory cytokines tumor necrosis factor alpha (TNF-alpha) and interleukin six (IL-6) in adipose may contribute to breast cancer pathogenesis." (PMID 38816709, 2024).
breast carcinoma (continued). "To investigate whether the inhibition of STAT3 by LINC01929 knockdown is mediated by TNF, we discovered that the cytokine TNF‐α is capable of activating both the TNF pathway and STAT3 in breast cancer cell lines." (PMID 39586790, 2024). "Additionally, MTX has demonstrated efficacy when paired with anti-tumor necrosis factor-alpha (TNF-α) drugs in the treatment of individuals suffering from ulcerative colitis, breast cancer, lung carcinoma, head and neck malignancies, and ovarian carcinoma." (PMID 38822868, 2024). "Additionally, it revealed a cooperative effect between IFN-γ and TNF-α in inducing the production of CCL5 and CXCL9 from breast cancer cells." (PMID 38167224, 2024). "Meanwhile, the supplementation of DMBA-induced breast cancer rats with Ajwa date extract induced a significant increase of NK cells while normalizing the level of TNF-α as compared to the non-treated group." (PMID 40259956, 2024). "In addition, one study found a correlation between a high expression of SLAMF8/CD353, tumor necrosis factor (TNF), and lymphocyte infiltration with a poor response to therapy in postmenopausal estrogen receptor (ER)+ breast cancer." (PMID 38476238, 2024). "Despite the clinical signs, which resemble the presence of acute inflammation, IBCs produce inflammatory cytokines (such as IFNG, TNF, IL1A, IL1B, and IL8) at similar levels to other breast cancer subtypes, while the host inflammatory cell infiltration is low in the IBC stroma." (PMID 39103878, 2024). "Unlike TNBC, ER+ breast cancers did not display age-stratified immune responses, apart from tumor necrosis factor alpha (TNFα) signaling, which was enriched in the younger cohort." (PMID 39483921, 2024). "IC50 concentrations were given to breast cancer co-culture models (MCF-7/THP-1 and MDA-MB-231/THP-1) planted and merged according to the procedure, and after 24 h using flow cytometry, IL-1β, IL-6 levels of IL-8, IL-10, and TNF-α were measured." (PMID 39175950, 2024). "Since both TGF-β and TNF-α are drivers of inflammation and cancer metastasis, and are co-expressed with MMP-9, we asked whether the co-exposure of breast cancer cells to TGF-β and TNF-α could amplify MMP-9 expression in these cells." (PMID 39351229, 2024). "In patients with breast cancer, elevated serum levels of TNF-α were not necessarily found when comparing early ductal carcinoma patients with healthy controls." (PMID 36980727, 2023). "Furthermore, studies have shown that TNF-α stimulates NF-κB, J.N.K., and the PI3K-AKT signaling pathway in human breast cancer cells." (PMID 38202644, 2023). "Peripheral blood samples were collected from 187 rural working women with breast cancer, occupationally exposed or not to pesticides, to quantify the levels of cytokines IL-1β, IL-12, IL-4, IL-17-A, and TNF -α." (PMID 37942322, 2023). "Thus, there were positive correlations among TNF-α, RELA and ATX, but these relationships need to be investigated further to understand their roles in the progression of breast cancer metastasis and patient survival." (PMID 38201482, 2023). "This study demonstrated IL‐1β, TNF‐α, and IL‐4 as potential pathways to CRCI in response to ongoing psychological distress, which provided evidence for the involvement of psychological distress in CRCI in breast cancer survivors." (PMID 36965094, 2023). "Tumors from humanized breast cancer models exhibited high levels of GMCSF, IL-6, IL-8, and TNFα." (PMID 36860657, 2023). "For instance, it was demonstrated that CCL2/monocyte chemoattractant protein-1, CCL5, IL-1β, IL-6, tumor necrosis factor α, vascular endothelial growth factor, and leptin released by CAAs in the TME promote the proliferation, and dissemination of breast cancer cells." (PMID 36980280, 2023). "Our group reported that TNFα-induced MUC4 is involved in HER2-targeted therapy resistance in vivo and in vitro, and that it is an independent predictor of trastuzumab response in HER2-positive breast cancer patients." (PMID 37284199, 2023).
breast carcinoma (continued). "Therefore, we analyzed the expression of TNF-α in the malignant neoplasms of digestive organs, bronchus or lung, nasopharynx, DLBC and breast cancer from GEPIA." (PMID 37428723, 2023). "Additionally, TNF-α is known to regulate CD44 and its isoform expression in different breast cancer cell lines via a different pathway to promote cell migration." (PMID 36979874, 2023). "Furthermore, clinical analyses were conducted for the sera samples of prostate and breast cancer patients for CRP, cytokines levels (IFN-γ, TNF-α and IL-6), and oxidative stress level markers (MDA and carbonyl contents)." (PMID 37153524, 2023). "Moreover, the role of TNF-α has been well established in the metastatic pathway of EMT in various solid cancers including lung and breast cancer." (PMID 37232720, 2023). "Also, TNF-α and LPA, in the present work, increased the size of clones formed by 4T1 breast cancer cells, which are highly metastatic." (PMID 38201482, 2023). "We investigated whether the TNF-α-regulated NF-κB pathway can control the expression of ATX, which is one of the upregulated genes in breast cancer." (PMID 38201482, 2023). "Luberto and collaborators previously reported a protective effect by the small molecule neutral sphingomyelinase inhibitor GW4869 in MCF7 breast cancer cells reducing nuclear condensation, caspase activation, PARP degradation and trypan blue uptake after apoptotic induction by tumor necrosis factor." (PMID 36010578, 2022). "Although the mechanism of the influence of TNF-α on the development of breast cancer is not proven yet, a wide body of literature demonstrates that TNF-α plays a role in linking the inflammation and the growth of breast cancer." (PMID 35928364, 2022). "In addition, through TNF-α signaling, TRAF4 exerts anti-apoptotic effects on breast cancer and osteosarcoma." (PMID 35242717, 2022). "Thus, a novel antitumor mechanism driven by TSLP-stimulated CD4+ T cells and delivered by TNF-α and IFN-γ cytokines results in the senescence of advanced breast cancer cells." (PMID 36467403, 2022). "Among the four classical subtypes of breast cancer, only TNBC was identified with significantly higher TNF expression than normal samples, suggesting that TNF-induced EMT may be specific to TNBC." (PMID 36291687, 2022). "Therefore, this meta-analysis will focus on the effects of exercise on IL-6, IL-10, IL-1β, CRP, TNF-α, IGF-1 and IGFBP-3 levels in breast cancer patients." (PMID 36482346, 2022). "In another prospective cohort study based on the Swedish biologics register (ARTIS), TNF inhibitor users did not experience more breast cancer recurrences than TNF inhibitor non-users among patients with RA and a history of breast cancer." (PMID 35945635, 2022). "On the other hand, TNFα blockers can inhibit the expression of MUC4 and then overcome the resistance of primary trastuzumab in HER2-positive breast cancer, and may also be used as a potential new therapeutic target." (PMID 36276152, 2022). "TNF-α plays a dual role in breast cancer—it can promote apoptosis and proliferation in different breast cancer cell lines, however, the original cellular response to TNF-α is increased proliferation and induction of breast cancer metastasis." (PMID 36232888, 2022). "In breast cancer, PEBP4 silencing can promote tumor necrosis factor-α (TNF-α)-induced apoptosis by activating mitogen-activated protein kinase (MAPK) signaling cascade, and suppress proliferation and invasion by repressing phosphoinositide 3-kinase (PI3K)/Akt pathway." (PMID 36120358, 2022). "In addition, promising anticancer results were obtained after treating the breast cancer cells with BV6 in combination with death ligands such as TNF-related apoptosis-inducing ligand (TRAIL) and Tumor necrosis factor-α (TNF-α)." (PMID 36358282, 2022).
breast carcinoma (continued). "Our primary objective was to determine the anti-tumor activity of cimetidine, vitamin C and their combination via targeting TAMC and its mediators (histamine, VEGF, and TNF-α) in the TME and investigating their effect on PI3K/AKT/mTOR cue in Ehrlich induced breast cancer in mice." (PMID 35798765, 2022). "We conducted two studies to examine differences in post-operative physical and mental functioning, pain, fatigue, and systemic inflammatory markers including interleukin (IL)-6, tumor necrosis factor (TNF)-α, and C-reactive protein (CRP) in women with early-stage breast cancer." (PMID 35941136, 2022). "They showed anticarcinogenic effects in breast tumors, mainly by ameliorating some pro-inflammatory cytokines IL-17, IL-2, IL-12, IFN-γ, and TNF-α, in addition to improving DTH and NK responses, decreased tumor volume, and prolonged survival in breast cancer animal model." (PMID 36290639, 2022). "ER+ MCF7 breast cancer cells expressing low levels of cIAP1/2 undergo apoptosis in response to SM-164 combined with TNFα but not with LPS." (PMID 36119107, 2022). "However, there are few studies on the combination of TNF-α, TSH, and p185 protein in the diagnosis of breast cancer." (PMID 35783155, 2022). "Finally, sarcopenia is related to proteolytic cascade reactions such as the release of tumor necrosis factor-α (TNF-α), which promotes tumor migration and invasion, thus further deteriorating the prognosis of breast cancer." (PMID 36203426, 2022). "This corroborates with previous study that suggested that TNF signaling is enriched in basal breast cancer than nonbasal breast tumors, along with other inflammatory pathways such as cytokine–cytokine receptor interaction and Toll‐like signaling." (PMID 34197030, 2022). "Together, our findings previously and in this report suggest that TNFα is essential for an IAP antagonist to treat cancer by inducing cancer cell apoptosis rapidly, and bacterial component LPS can also induce breast cancer cell apoptosis through TLR4 stimulating TNFα production by the host cells." (PMID 36119107, 2022). "Breast cancer cell lines BT-474, MCF7, Hs-578-T, MDA-MB-231, MDA-MB-453, and MDA-MB-468 were cultured in different medium and then treated with 100 or 500 nM GDC-0941, 100 nM OSU-T315, or TNF-α antibody." (PMID 35477364, 2022). "Anti-TNF-α treatment using a monoclonal antibody (infliximab) against a TNF receptor appears to repress tumor growth, induce tumor degeneration, and inhibit bone metastases in breast cancer-induced mice." (PMID 36140220, 2022). "For this reason, in a female mammary tumor model, we studied whether BPA treatment could affect the intratumoral expression of IL-1β, IL-4, IL-6, IL-10, TNF-α, IFN-γ, and VEGF by confocal microscopy immunofluorescence." (PMID 35269666, 2022). "The effect of TNFα on the enzymatic activity of SphK1/2 in MCF-7 breast cancer cells was never tested comprehensively." (PMID 33919234, 2021). "In our study, the TIMER webserver showed a negative correlation of CI and CIII subunits with TNF-α in basal breast cancer patients." (PMID 33926547, 2021). "Gene-set enrichment analysis has shown that important pathways are upregulated in response to SK1 knockdown in prostate and breast cancer cells, like KRAS, IL2/STAT5, EMT and TNF/NFκB, indicating that switching off one pathway is insufficient to completely block cancer cell growth." (PMID 34043703, 2021). "In another breast cancer study, levels of IL-7, IL-8, IL-13, macrophage migration inhibitory factor (MIF), and TNF-β were increased, whereas those of CTACK, G-CSF, HGF, IL-1β, and TNF-α were decreased after IORT exposure." (PMID 34641806, 2021). "MCF-7 breast cancer cells exposed to environmentally relevant concentrations of DDT exhibit upregulation of inflammatory and oxidative stress marker genes such as CXCL8, HMOX-1, and TNF." (PMID 35008370, 2021).
breast carcinoma (continued). "This work also showed that neutrophils from patients with and without breast cancer exposed to TNF-α ex-vivo exhibited enhanced cytotoxicity, with even further cytotoxicity seen in patients with breast cancer." (PMID 33986746, 2021). "TNF-α was found to have 100% specificity and sensitivity in distinguishing breast cancer patients with metastases from patients without metastasis (when the cut-off value is selected as 12.33 pg/mL), and high-grade patients from lowintermediate grade patients." (PMID 33776564, 2021). "The inclusion of cancers other than breast cancer may have influenced the findings for IL-6 and IL-8, but Khosravi did show that CRP and TNF were more sensitive to exercise changes." (PMID 34777343, 2021). "CIII subunits like UQCR10, UQCRB, and UQCRQ expression were also altered in basal breast cancer patients which showed a significant negative correlation with TNF-α expression as compared to luminal breasts cancer patients." (PMID 33926547, 2021). "We observed that TNF-α differentially modulate the subunits of oxidative phosphorylation (OXPHOS) complexes and mitochondrial functions to regulate the clonogenic and migration abilities of the breast cancer cells." (PMID 33926547, 2021). "We found that when a panel of five phenotypically diverse human breast cancer cell lines was subjected to treatment with sunitinib plus recombinant Th1 cytokines IFN-γ and TNF-α, synergistic effects were observed across a number of parameters including different aspects of apoptotic cell death." (PMID 33936816, 2021). "The regulation of TNF-α mediated mitochondrial complex assembly and its role in the regulation of tumorigenic potential of different breast cancer cell types had not been systemically investigated." (PMID 33926547, 2021). "Herein, we determined whether TNF-α could induce IP-10 production in metastatic breast cancer MCF-7 cells and if so, which signal transduction pathway(s) were involved in TNFα-driven IP-10 induction." (PMID 34572567, 2021). "We predict therefore that TNF-α may differentially regulate the AWP1 protein level in breast cancer cells and that AWP1 acts as a negative regulator of TNF-α-induced cancer promoting processes." (PMID 33816268, 2021). "TNF-α, IL-6, and IL-8 were significantly reduced after 6 months in the SHD group, but not in the control group, and this indicated that SHD can significantly improve the inflammatory response of patients with breast cancer treated with endocrine therapy." (PMID 34485118, 2021). "To verify this hypothesis, in the present study we examined the specific effect of TNFα on the promotion of tamoxifen sensitivity in ERα-positive breast cancer and identified NCOR1 as a key regulator acting downstream of TNFα." (PMID 34073371, 2021). "In our recent study, we demonstrated that tumor necrosis factor α (TNFα), a multifunctional inflammatory cytokine, selectively triggers apoptotic cell death in ERα-positive, but not ERα-negative, breast cancer." (PMID 34073371, 2021). "In our current study, we found that an AWP1 knockdown using short hairpin RNAs increases the migratory potential of non-aggressive MCF-7 breast cancer cells with no significant alteration of their proliferation in response to TNF-α." (PMID 33816268, 2021). "Additionally, co-culture of otherwise weakly metastatic (dormant) breast cancer cells with MC3T3-E1 osteoblasts increased breast cancer growth in vitro when stimulated with IL-1ß and TNF-α." (PMID 33809315, 2021). "Here we will address whether rapid NFκB activation by TNF, which is enabled by the degradation of IκBα within the IκBα-NFκB complex, is critical for activation of NFκB target genes in MCF7 breast cancer cells." (PMID 34853340, 2021).